TIMP1 (TIMP metallopeptidase inhibitor 1)
Diseases named in the same sentence as TIMP1 in open-access papers (continued):
Sharing a sentence is not in itself a finding about the gene and the disease.
liver fibrosis (continued). "Although an increased level of tissue inhibitor of metalloproteinases (TIMP-1) has been proposed as a laboratory biomarker in the diagnosis of TAK, it is poorly specific, often occurring also in psoriasis, liver fibrosis, and cancer." (PMID 33026580, 2021). "Many of these genes, including COL1A1, LOX, MMP14, TGFB3, TIMP1 and VCAN, are known markers for liver fibrosis." (PMID 34588551, 2021). "RNA and protein‐based analyses confirmed that CKI resulted in diminished expression of liver fibrosis‐related genes TGF‐β1, COL1A, Fibronectin, and TIMP1 in a dose‐dependent manner, which were upregulated in TGF‐β1‐treated LX‐2 cells." (PMID 34323416, 2021). "The Enhanced Liver Fibrosis (ELF) panel contains three matrix turnover proteins [hyaluronic acid (HA), tissue inhibitor of metalloproteinase 1 (TIMP‐1) and N‐terminal procollagen III‐peptide (PIIINP)]." (PMID 33102798, 2020). "Our results show that neratinib treatment significantly ameliorates both stages of liver fibrosis mice, as confirmed by the reductions in α-SMA expression, collagen deposition, and other fibrogenic markers (TIMP-1, PDGFR-β, and TGF-β) in liver tissues." (PMID 32901093, 2020). "Indicating that the inhibition of PPARγ in HSC is responsible for the increased transcription of TIMPs, the overexpression of PPARγ reduces the expression of TIMP1, TIMP2, and alpha smooth muscle actin (αSMA) and reverses hepatic fibrosis." (PMID 32660130, 2020). "In order to detect the effect of ICQA on liver fibrosis, the expressions of TGF-β1, TIMP-1 and COL1α1in rat liver were detected in our study." (PMID 32425800, 2020). "We further analyzed MMP-2, MMP-9, MMP-13 and tissue inhibitor of matrix metalloproteinases 1 (TIMP-1) hepatic gene expressions after BDL- and CCl-4-induced liver fibrosis using RT-PCR." (PMID 30875826, 2019). "TIMPs are associated with the regulation of MMP activities, and particularly, TIMP-1 and TIMP-2 are reported to be highly expressed in human liver fibrosis." (PMID 31861943, 2019). "In the present vitamin D supplementation study, we assessed liver fibrosis by HA, PIIINP, and TIMP-1, each of which reflect ongoing sinusoidal fibrogenesis and fibrolysis in the liver, and their composite ELF score." (PMID 30658483, 2019). "Recently, an increase of pro-MMP-2 accompanied by increased TIMP-1 and TIMP-2 levels in NAFLD liver fibrosis has been reported." (PMID 30769840, 2019). "Our data indicate that KFXOL dramatically inhibited TIMP-1 expression, which is consistent with previous observations on the activity of P. americana extracts in rats with CCL4-induced hepatic fibrosis." (PMID 31885648, 2019). "This antifibrotic effect was associated to the decrease of fibrogenic markers involved in liver fibrosis progression, such as the transforming growth factor (TGF-β), the α-smooth muscle actin (α-SMA), and the tissue metalloproteinases inhibitor (TIMP-1)." (PMID 30647809, 2018). "The results indicated that ZLE has antifibrotic activity by reversing S. mansoni-induced liver fibrosis through reducing hepatic expression of TGF-β1, MMP-9, and TIMP-1 and increasing antioxidative status while limiting apoptosis." (PMID 30273397, 2018). "In comparison to that, the findings of this study show that PZQ appears to be effective in decreasing hepatic fibrosis, as demonstrated by a clear change in the hepatic expression of α-SMA, TGF-β1, TIMP-1, and MMP-9." (PMID 30273397, 2018). "In mice affected by liver fibrosis, the levels of TGF-β, α-SMA, and TIMP1 significantly increased compared to healthy mice." (PMID 30647809, 2018). "Since NASH also manifests hepatic fibrosis, we also analyzed two fibrosis markers — alpha-smooth muscle actin (α-SMA) and TIMP1, in liver sections." (PMID 28300161, 2017). "The results of our experiments showed that quercetin reduced BDL or CCl4 liver fibrosis, inhibited extracellular matrix formation, and regulated matrix metallopeptidase (MMP)-9 and tissue inhibitor of metalloproteinase (TIMP)-1." (PMID 28839277, 2017).
liver fibrosis (continued). "More recently, an adiponectin agonist reversed liver fibrosis in mice by attenuating the expression of the fibrogenesis markers α-SMA, TGF-β1, CTGF, and tissue inhibitor of metalloproteinase I (TIMP1)." (PMID 28498357, 2017). "Dysregulated TIMP-1 has been previously reported in SSc, and TIMP-1 is critical in hepatic fibrosis." (PMID 26762516, 2016). "We found that upregulation of TIMP-1 via ERK activation was required for EPM-mediated liver fibrosis, because blockade of EPM using an shRNA in HSCs significantly reduced ERK activation and TIMP-1 expression." (PMID 27362846, 2016). "A statistically significant correlation was found in HCV monoinfected and HIV/HCV coinfected subjects between TIMP-1 plasma levels and liver stiffness at time of recruitment, indicating the existence of a relationship between TIMP-1 and liver fibrosis." (PMID 27023536, 2016). "Liver fibrosis improved upon administration of OM, as assessed by reduced deposition of collagen and reduced expression of genes co-occurring with liver fibrosis, such as MMP-2, TIMP-1, and type I procollagen." (PMID 26941644, 2016). "The Enhanced Liver Fibrosis (ELF®) score is a panel combining these three direct markers (HA, TIMP-1 and PIIINP) that have demonstrated a good correlation with liver fibrosis stage." (PMID 27984583, 2016). "It has been known that the expression levels of MMP2, MMP9, TIMP1 and TIMP2 mRNAs are increased in the patients with hepatic fibrosis." (PMID 26863419, 2016). "Activated hepatic stellate cells contribute to liver fibrosis via abnormal production of MMP2, TIMP1, and TIMP2 through the secretion of various inflammatory cytokines from Kupffer cells and T cells." (PMID 26358689, 2015). "Measurements of other new potential biomarkers for staging liver fibrosis such as fibulin-5, MMP-2 or TIMP-1 further have the potential to improve the accuracy of non-invasive estimates of liver fibrosis." (PMID 26460565, 2015). "Consistently, real-time PCR analysis also confirmed higher expression of liver fibrosis-related genes TGF-β1, collagen-1 and TIMP1 in the liver from gankyrinhep mice than that from littermates." (PMID 25950481, 2015). "Treatment with betulin and betulinic acid inhibited expression of TNF-α, TGF-β1, tissue inhibitor of metalloproteinase (TIMP)-1, TIMP-2, and activated matrix metalloproteinase (MMP)-2 in alcohol-induced liver fibrosis in vivo." (PMID 25897319, 2015). "In the present study, CCl4 increases TIMP-1 expression so EGF expression decreases, leading to liver fibrosis due to the accumulation of collagen in the liver." (PMID 26062544, 2015). "Thus, deletion of TIMP-1 could accelerate liver fibrosis by increasing liver injury." (PMID 23755201, 2013). "TIMP-1 has been demonstrated to suppress apoptosis in HSCs and reduce MMP activity, which strongly promoted the development of liver fibrosis in a transgenic mouse model." (PMID 24129183, 2013). "That study also reported that TIMP-1 and TIMP-2 are crucial factors for promoting the progression of liver fibrosis." (PMID 24223741, 2013). "A more recent development, the Enhanced Liver Fibrosis (ELF) test, uses tissue inhibitor of metalloproteinase 1 (TIMP-1), hyaluronic acid and procollagen III amino terminal peptide (PIIIP)." (PMID 22761838, 2012). "The ELF (Enhanced Liver Fibrosis) score is a serum biomarker panel that measures three collagen metabolites: type III procollagen amino terminal propeptide (PIIINP), tissue inhibitor of metalloproteinases-1 (TIMP-1), and hyaluronic acid (HA)." (PMID 40969805, 2025). "In addition, MSCs upregulate MMPs (e.g., MMP9 and MMP13) and inhibit the expression of TIMPs (e.g., TIMP-1), which directly degrade ECM to alleviate liver fibrosis." (PMID 38360740, 2024). "The Enhanced Liver Fibrosis (ELF) test is a more advanced serum biomarker that measures direct markers of fibrosis, including hyaluronic acid, procollagen III amino-terminal peptide (PIIINP), and tissue inhibitor of metalloproteinases-1 (TIMP-1)." (PMID 39606621, 2024).
liver fibrosis (continued). "Our data suggest the capacity of ITRCZ-Cht NPs to modulate the potential crosstalk between Hedgehog and other signaling molecules (TGF-β, TIMP-1, PDGF-BB) in liver fibrosis, however, further experimental work is required to confirm this hypothesis." (PMID 38808257, 2024). "One of the comprehensive NITs is the enhanced liver fibrosis (ELF) test, which is based on testing markers of acute phase reactants, such as hyaluronic acid (HA), type III procollagen peptide (PIIINP) and tissue inhibitor of metalloproteinase-1 (TIMP1)." (PMID 37109712, 2023). "TGF-β is secreted by a variety of immune cells through the Smad pathway; further promoting the elevated levels of TIMP1, α-SMA, and collagen 1/2 during the HSC to myofibroblast transition, formatting and remodeling the ECM, and eventually leading to liver fibrosis." (PMID 36986363, 2023). "Moreover, a mechanistic study has revealed that FZHY can decrease the expression levels of α-SMA, CTGF, TIMP-1, TGF-β1, and Smads, thereby reducing hepatic apoptosis, acute liver injury, and liver fibrosis." (PMID 37025490, 2023). "Thus, the effects of corylin on the expression of TIMP-1 and MMP-9 in macrophages and Kupffer cells should be further studied to clarify the mechanism by which corylin inhibits liver fibrosis." (PMID 38069259, 2023). "Furthermore, the HSD increased the levels of inflammatory cytokines and indicators of liver fibrosis (alpha smooth muscle actin [α-SMA], collagen I, TGF-β, tissue inhibitor matrix metalloproteinase 1 [TIMP-1], and PDGF)." (PMID 36786636, 2023). "Furthermore, the pharmacological effects of P. chinense on these proteins were verified by CCl4-induced rat liver fibrosis, and P. chinense was found to improve liver functions through regulating TNF-α, Timp1, and HO-1 expressions." (PMID 35721129, 2022). "In addition, the hepatic expressions of TIMP1 and α-SMA that related to hepatic fibrosis were also increased in the mice from the HFD group but were suppressed in the mice from SMRR-polysaccharide-supplied groups." (PMID 36142520, 2022). "The Enhanced Liver Fibrosis (ELF) test is a commercially available algorithm that includes three serum biomarkers: hyaluronic acid (HA), the N-terminal pro-peptide of collagen type III (PIIINP), and tissue inhibitor of metalloproteinase-1 (TIMP1)." (PMID 36589424, 2022). "The Enhanced Liver Fibrosis (ELF) score is a collagen marker set consisting of procollagen type III amino terminal propeptide (PIIINP), tissue inhibitor of metalloproteinases 1 (TIMP-1), and hyaluronic acid (HA)." (PMID 35177989, 2022). "In addition, a medium dose of Ganweikang tablet significantly reduced the increase in liver fibrosis indicators, including TGF-β1, Timp-1, Col1α1, and Col1α2 in NASH mice." (PMID 35774609, 2022). "Many predicted targets such as TIMP1, MMP2, COL1A1, MMP7, and COL3A1 have been involved in liver fibrogenesis and could be potential therapeutic targets for liver fibrosis." (PMID 35791909, 2022). "HFFs treatment also could down-regulate the LN and PCIII of liver tissues, the indicators of liver fibrosis evaluated by ELISA and significantly decreased α-SMA, collagen I, TGF-β, TIMP1, and MMP9 expressions evaluated by Q-PCR, similar to UC-MSCs treatment." (PMID 35831878, 2022). "Consistently, the upregulation of hydroxyproline, serum ALT and AST levels, and hepatic protein level of α-SMA and mRNA levels of Col1α1, Acta2 and TIMP-1 were also increased in IFN-γ-/- Vγ4 cells reconstituted mice, while IL-17-/- γδ T cells still showed protection against hepatic fibrosis." (PMID 35361750, 2022). "In the present study, the effects of L‐THP treatment on HSCs activation and ECM production in liver fibrosis were assessed by determining mRNA and protein expressions of Col‐1, α‐SMA, TIMP1 and MMP2 in the liver tissues from the two different liver fibrosis models." (PMID 33438347, 2021).
liver fibrosis (continued). "Hepatic protein levels of TGF-β1, known for pro-fibrogenic cytokine to promote HSCs activation or proliferation were drastically normalized by GF and other proteins such as TIMP-1, MMP-1, and MMP-13 which are known as ECMs promoters or degradations as responses of liver fibrosis." (PMID 34829709, 2021). "TIMP1 is an inhibitor of MMPs and thus promotes fibrogenesis but is not required to induce liver fibrosis." (PMID 34712238, 2021). "In an attempt to identify noninvasive markers of liver fibrosis during chronic hepatitis C, the Enhanced Liver Fibrosis (ELF) test was put forward; it evaluates the serum levels of TIMP1, HA, and N-terminal peptide of procollagen type III (PIIINP) and includes age for statistical robustness." (PMID 34065048, 2021). "The aim of this study is to explore the usefulness of the Enhanced Liver Fibrosis score (ELF), procollagen-III aminoterminal propeptide (PIIINP), tissue inhibitor of matrix metalloproteinase-1 (TIMP-1), and hyaluronic acid (HA) in assessing vascular damage in TA patients." (PMID 34940542, 2021). "MMP-1 and TIMP-1 are closely related to liver fibrosis, however, we do not know their role in early stage of liver fibrosis such as chronic hepatitis or even acute hepatitis." (PMID 34611503, 2021). "The mRNA levels of the fibrotic markers, Col1a1 and Timp1, were also elevated, but no significant signs of liver fibrosis were observed by Sirius-red staining of liver sections of WT and IKKβca;A20LKO mice." (PMID 34626855, 2021). "Atractylodes macrocephaia was found: to recover the elevated levels of hyaluronic acid, laminin, type IV collagen, type III procollagen, and TGF‐β1; to suppress procollagen I, collagen III, and TIMP‐1 expression; and to improve the TIMP‐1/MMP‐13 ratio in rat liver fibrosis." (PMID 32705795, 2020). "Furthermore, the reduction of liver fibrosis was confirmed in mice receiving PD‐MC by quantitatively analyzing hydroxyproline and fibrotic markers such as, Col1α1, TGF‐β, and TIMP‐1." (PMID 32274310, 2020). "Specifically, the cutoff values for FIB-4, hyaluronic acid, platelet count, enhanced liver fibrosis score, 7S collagen, APRI, M2BPGi, PIIINP and TIMP-1 were 2.78, 110.63 ng/mL, 11.9 × 103/μL, 11.75, 6.1 ng/mL, 0.89, 1.47 cutoff index (C.O.I.), 0.6 ng/mL and 379.9 ng/mL, respectively." (PMID 33138335, 2020). "The enhanced liver fibrosis (ELF) test is a non-invasive blood test that measures three direct markers of fibrosis: hyaluronic acid (HA), procollagen III amino-terminal peptide (PIIINP), and tissue inhibitor of matrix metalloproteinase 1 (TIMP-1)." (PMID 32570776, 2020). "Moreover, emodin also protected against liver fibrosis and HSC activation by reducing TGF-β1 and Smad4 expression and inhibiting tissue inhibitor of metalloproteinases-1 (TIMP-1) expression, and epithelial-mesenchymal transition." (PMID 33082829, 2020). "Furthermore, the IGFBPrP1 knockdown attenuated liver fibrosis by re-establishing the MMP2/TIMP2 and MMP9/TIMP1 balance concomitant with the inhibition of HSCs activation and degradation of the ECM." (PMID 30769840, 2019). "Moreover, NEMOΔhepa/Faslpr animals elicited significantly decreased parameters of liver fibrosis, such as Collagen IA1, MMP2, and TIMP1, and reduced proinflammatory macrophages and cytokine expression." (PMID 30737368, 2019). "Thus, TIMPs inhibit the expression of TIMP1 and weaken the inhibition of MMP1, which promotes ECM degradation and exerts an anti-liver fibrosis effect." (PMID 29986685, 2018). "Thus, the expression of many hepatic fibrosis markers such as Col1A1, FN1, MMP9 and TIMP1 was more abundant in GWI-BDL group than in naïve-BDL controls." (PMID 30177688, 2018). "WFA-M2BP and ELF score are more specific to the kinetics of liver fibrosis progression than are AST, ALT, and Plt because WFA-M2BP, hyaluronic acid, PIIINP, and TIMP-1 are secreted by the key player of liver fibrogenesis; activated hepatic stellate cells or myofibroblasts." (PMID 30208564, 2018).
liver fibrosis (continued). "The expression levels of several hepatic fibrosis markers such as alpha smooth muscle actin (αSMA), collagen type 1 alpha 1 chain (Col1A1), fibronectin 1 (FN1), PCNA and tissue inhibitor of metalloprotease 1 (TIMP1) were tested by RT-qPCR." (PMID 29125588, 2017). "TIMP1, which has been demonstrated to reduce MMP activity, plays an important role in the progress of liver fibrosis and it is an important target for the treatment of liver fibrosis." (PMID 29311932, 2017). "In liver fibrosis, ghrelin has been found to inhibit extracellular matrix formation by maintaining the balance between matrix metalloproteinases (MMP2) and tissue inhibitor of matrix metalloproteinases (TIMP1)." (PMID 29100513, 2017). "In addition, levels of TIMP-1 and VEGF, which stimulate the development of hepatic fibrosis, were also promoted under DMN application." (PMID 29179490, 2017). "This imbalance toward TIMP-1 may justify the highest levels of stiffness in HCV monoinfected individuals, suggesting that the TIMP-1/MMP-9 ratio mirrors the progression of hepatic fibrosis better than TIMP-1 levels." (PMID 27023536, 2016). "Given the important role of TIMP-1 in the process of fibrogenesis, we hypothesized that HIV+HCV co-infection produces an environment that accelerates liver fibrosis in an EPM-dependent manner in the cell model." (PMID 27362846, 2016). "TIMP-1 and TIMP-2 are capable of inhibiting the activities of all known MMPs and, in consistent with our results, their expressions are increased in CCl4-induced liver fibrosis." (PMID 27776513, 2016). "In contrast to its potential protective role in liver fibrosis, TIMP-1 does not impact the development or extent of lung fibrosis in response to bleomycin." (PMID 24713275, 2014). "Recently, a liver fibrosis score, namely ELF, which combines the serum concentrations of substances related to collagen metabolism (PIIINP) and tissue remodeling (TIMP-1 and HA), has progressively been incorporated among the most common diagnostic tools to evaluate liver fibrosis." (PMID 25275549, 2014). "Taking into account our previous results on fibrogenesis process direct markers, we propose the addition of apoptosis markers, particularly sFas combined with TIMP-1 in pediatric patients and sFas with TGF-ß1, HA, PIIINP in adult patients to more accurately assess liver fibrosis severity." (PMID 23326448, 2013). "As TIMP-1 protects against HSC death and hepatocyte apoptosis, we speculate that TIMP-1 may have dual roles in liver fibrosis: stimulating liver fibrosis via promoting HSC survival and inhibiting liver fibrosis via preventing liver injury." (PMID 21711826, 2011). "Classical fibrotic mediators and markers (including Tgfb1, Timp1, and Vcam1), collagen of the ECM (including Col4a1, Col4a2, Col16A1, and Col18a1) and cell surface adhesion and signaling integrin (Itga2, Itga5) were found to be differentially expressed in the enriched hepatic fibrosis pathways." (PMID 39747668, 2025). "API effectively alleviates CCl4-and bile duct ligation (BDL)-induced liver fibrosis by reducing liver enzyme levels, inhibiting ECM production, and regulating the balance between matrix metalloproteinase 2 (MMP2) and tissue inhibitors of metalloproteinase 1 (TIMP1)." (PMID 39749193, 2024). "Moreover, this hypothesis can be supported by the close involvement of Timp1 and Mmps as its first neighbors in the processes of ECM organization and tissue remodeling as well as participation in the pulmonary and liver fibrosis." (PMID 36675165, 2023). "Moreover, TIMP1 serum concentration serves along hyaluronic acid and procollagen type 3 N-terminal propeptide (PIIINP) to calculate the Enhanced Liver Fibrosis (ELF) score for advanced liver fibrosis assessment (ELF ≤ 9.8 to rule out advanced LF, ELF > 11.3 to rule in advanced LF)." (PMID 37445827, 2023).